LINC-PINT (long independently transcribed non-coding RNA, p53 induced transcript)
Diseases named in the same sentence as LINC-PINT in open-access papers (continued):
Sharing a sentence is not in itself a finding about the gene and the disease.
tumor (49 papers, 2013 to 2025). "In our research, we first proved that LINC-PINT was strongly associated with an increase in tumor cell invasion and migration, whereas AC108449.2 and AC007637.1 showed the opposite effect." (PMID 37341994, 2023). "In the present study, LINC-PINT mRNA expression level was significantly associated with variables such as tumour differentiation and tumour stage." (PMID 36087249, 2022). "Overexpression of the LINC-PINT impairs DNA damage repair, leading to DNA damage accumulated and rendering the tumor cells susceptible to ionizing radiation." (PMID 33963177, 2021). "Additionally, bioinformatics analysis showed that LINC-PINT expression was observed to be linked with Tumor Mutational Burden (TMB) and Microsatellite Instability (MSI) in tumors, the results of bioinformatics were verified by qRT-PCR." (PMID 38553526, 2024). "Subsequently, we further examined the relationship between LINC-PINT expression and tumor staging by utilizing the UNCLAN database." (PMID 38553526, 2024). "In our pursuit to comprehensively explore the impact of LINC-PINT expression on tumor survival outcomes, we conducted additional K-M analyses." (PMID 38553526, 2024). "We initiated our investigation by scrutinizing the expression patterns of LINC-PINT within the extensive TCGA dataset, encompassing both normal tissues and tumor tissues." (PMID 38553526, 2024). "Then, we analyzed differential expression of LINC-PINT between tumor and adjacent non-tumor tissues within the TCGA cohort." (PMID 38553526, 2024). "Conversely, in distinct tumor categories such as KIRC, PRAD, COAD, and HNSC, heightened LINC-PINT expression was linked to poorer prognostic outcomes." (PMID 38553526, 2024). "Some existing studies have demonstrated the close correlation between LINC-PINT dysregulation and tumor progression and treatment effect." (PMID 38553526, 2024). "To comprehensively summarize these relationships, we have classified them into four distinct categories as follows: Firstly, LINC-PINT actively participates in the regulation of tumor proliferation, invasion, and metastasis by the following ways." (PMID 38553526, 2024). "In order to further elucidate the prognostic value of LINC-PINT across various cancers, we conducted a univariate COX regression analysis to explore the potential correlation between LINC-PINT expression levels and tumor survival outcomes." (PMID 38553526, 2024). "Mechanistically, LINC-PINT interacts with PRC2 at a few tumor-invasion-related gene loci, such as Early Growth Response 1 (EGR1) and Integrin alpha 3 (ITGA3), and induces their silencing, ultimately repressing cancer cell migration." (PMID 36750826, 2023). "Analogously, LINC-PINT was highly expressed in ccRCC cell lines and tumor tissues, especially in patients with advanced stage, T-stage and M-stage, while AC108449.2 and AC007637.1 showed the opposite results." (PMID 37341994, 2023). "In the present study, we demonstrated for the first time that the starvation-induced tumor microenvironment significantly upregulated the expression of LINC-PINT and downregulated the expression of AC108449.2 and AC007637.1 in a time-dependent manner." (PMID 37341994, 2023). "LINC-PINT is over-expressed in tumor tissues and can further promote ccRCC metastasis under starvation conditions, while AC108449.2 and AC007637.1 show the opposite results." (PMID 37341994, 2023). "The expression level of LINC-PINT was significantly higher in tumor tissues than in adjacent normal tissues, but AC108449.2 and AC007637.1 were contrary." (PMID 37341994, 2023). "For instance, lncRNA LINC-PINT has been identified as a tumor suppressor caRNA in many classes of cancers." (PMID 36750826, 2023).
tumor (continued). "LINC-PINT, which displays low expression levels in tumours, operates as a suppressor of cancer progression and an inverse relationship between the expression of LINC-PINT and the aggressiveness of the tumours exists." (PMID 36087249, 2022). "In the present study, more than 55% of patients displayed reduced LINC-PINT expression, this downregulation was significantly related to pathological information including tumour location, tumour stage and differentiation." (PMID 36087249, 2022). "We investigated the effects of LINC-PINT on DDP-resistance in tumor-bearing nude mice treated with DDP." (PMID 36091809, 2022). "Studies have shown that LINC-PINT plays a key role in tumor suppressor activity and is downregulated in many cancers." (PMID 36091809, 2022). "Expression levels of LINC-PINT were downregulated in CRC tumour tissues compared with adjacent normal tissues, where 56% of cancerous patients demonstrated a decrease and 44% of patients had an increase in the mRNA level of LINC-PINT." (PMID 36087249, 2022). "Here, we showed that LINC-PINT functioned as a tumor suppressor in NPC, and its expression was negatively related to prognosis." (PMID 33963177, 2021). "The tumor suppressive role of LINC-PINT has been illuminated in cancers, whereas, the knowledge for its role in LSCC is still insufficient." (PMID 34257531, 2021). "The expression of LINC-PINT was approximately 2.85-fold lower in tumor tissues (n = 90) than in the control group (n = 7), which was consistent with the analysis of NPC cell lines." (PMID 33963177, 2021). "P52-regulated lncRNA LINC-PINT has a highly conserved sequence that is significant for its tumor suppressive role through specifically interacting with PRC2." (PMID 34257531, 2021). "The tumor inhibition rate in the LINC-PINT-overexpressing group was 51.2%, which was significantly higher than 20.1% in the control group." (PMID 33963177, 2021). "Collectively, our data emphasized the tumor suppressor role of LINC-PINT in NPC, given decreasing cancer cell proliferation by arresting the cell cycle and increasing apoptosis." (PMID 33963177, 2021). "After studying the in vitro roles of LINC‐PINT, in vivo assays were conducted in a xenograft tumor model." (PMID 31981466, 2020). "What’s more, tumor peritoneal metastasis experiment proved that LINC-PINT suppressed GBM invasion in vivo." (PMID 33505307, 2020). "Then we performed colony formation assay in LN229 cells and CCK8 assay in U87 and LN229 cell lines to determine the effect of LINC-PINT on tumor cell proliferation and viability in GBM." (PMID 33505307, 2020). "Taken together, LINC-PINT was in the upstream of Wnt/β-catenin pathway and suppressed tumor proliferation, invasion, and EMT by blocking Wnt/β-catenin signaling in GBM." (PMID 33505307, 2020). "For example, downregulated LINC‐PINT has been demonstrated to be correlated with the advanced tumor stage and bad survival in various cancers." (PMID 31981466, 2020). "Together, our study confirmed that LINC-PINT suppressed EMT as well as tumor proliferation and invasion via inhibiting Wnt/β-catenin signaling pathway in GBM." (PMID 33505307, 2020). "In previous study, LINC-PINT has been verified to act as a tumor suppressor in various kinds of cancers." (PMID 33505307, 2020).
tumor (continued). "In sum, our study exhibited that LINC‐PINT functioned as a tumor inhibitor during NSCLC progression and revealed a novel ceRNA regulatory pathway by sponging miR‐543 and activating PTEN." (PMID 31981466, 2020). "Mechanistically, we showed that LINC-PINT recruited EZH2 to the promoter region of its target genes to impede tumor cell proliferation." (PMID 31921860, 2019). "The overexpression of LINC-PINT in tumor cells resulted in significant tumor growth reduction and migration inhibition in A375, Mum2B and CRMM1 cells." (PMID 31921860, 2019). "To investigate the ability of LINC-PINT to suppress tumor formation in vivo, we established a xenograft model in nude mice using A375 cells." (PMID 31921860, 2019). "We find that LINC-PINT is downregulated in multiple types of cancer and acts as a tumor suppressor lncRNA by reducing the invasive phenotype of cancer cells." (PMID 29078818, 2017). "The experiments revealed that the lack of CE1 (deletions ΔCE1 and ΔCE1-2) totally abolished the effect of LINC-PINT in invasiveness and tumor formation." (PMID 29078818, 2017). "Our findings demonstrate the involvement of the downregulation of LINC-PINT in cancer progression and tumor malignancy." (PMID 29078818, 2017). "We found that LINC-PINT acts as tumor suppressor lncRNA that inhibits the migration capacity of cancer cells by repressing an invasion gene signature in a PRC2-dependent manner." (PMID 29078818, 2017). "Furthermore, LINC-PINT has been shown to cooperate with other LncRNAs in the joint regulation of tumor progression." (PMID 38553526, 2024). "Furthermore, decreasing LINC-PINT expression indicates advanced clinical tumour stages and a bad prognosis." (PMID 40176927, 2024). "Moreover, despite the novel findings stemming from bioinformatics analyses, further in vitro and in vivo studies are warranted to validate the molecular mechanisms by which LINC-PINT modulates tumor development and drug resistance." (PMID 38553526, 2024). "Additionally, qRT-PCR results revealed expression differences of LINC-PINT between tumor cell lines and normal cell lines, aligning with our bioinformatics analysis findings." (PMID 38553526, 2024). "Indeed, the abnormal expression of LINC-PINT reflects many vital predictors of cancer outcomes such as lymph node metastasis, tumor size, and differentiation status." (PMID 37006616, 2023). "In addition, we found that LINC-PINT was highly expressed in the ccRCC tumor tissues, while the expressions of AC108449.2 and AC007637.1 were higher in adjacent normal tissues than that in ccRCC tissues." (PMID 37341994, 2023). "Interestingly, the tumor suppressor PTCSC3 was studied along with LINC-PINT in gastric cancer tissues, inhibiting tumor growth and stemness when both were over-expressed." (PMID 35978835, 2022). "In addition, the sensitivity to DDP of tumor harboring LINC-PINT overexpression was significantly increased." (PMID 36091809, 2022). "LINC-PINT functions as a tumor suppressor and is downregulated in multiple cancers." (PMID 33963177, 2021). "LINC-PINT was originally identified as a tumor suppressor in various cancers." (PMID 33963177, 2021). "However, a recent study of human and mouse orthologues of LINC-PINT showed that both have tumour-suppressor activity in cell lines, acting through a relatively short, conserved region." (PMID 32024996, 2020). "In summary, LINC-PINT suppressed tumor invasion and migration of GBM cell lines in vitro." (PMID 33505307, 2020).
tumor (continued). "We found that LINC-PINT overexpression notably repressed tumor progression." (PMID 31921860, 2019). "We then examined LINC-PINT expression in different tumor cells." (PMID 31921860, 2019). "However, as the clone of LINC-PINT, the methylation of this gene has been functionally related to multiple tumor subtypes." (PMID 31480430, 2019). "Collectively, these observations show that the expression of LINC-PINT is inversely correlated with degree of malignancy and suggest that it could act as a tumor suppressor in different types of cancer." (PMID 29078818, 2017). "The expression of Linc-pint was much lower in PCa tumors compared to adjacent tissues, indicating that Linc-pint might act as a tumor suppressor in PCa." (PMID 27708234, 2016). "In terms of the association determination of LINC-PINT with clinicopathological parameters, down regulations in expression levels of LINC-PINT were significantly associated with CRC stage (p value: 0.01), tumour location (p value: 0.02) and distant metastasis (p value: 0.008)." (PMID 36087249, 2022). "In addition, Kaplan–Meier curves for overall survival and disease-free survival showed that patients with high expression level of LINC-PINT lived a good survival time, which further predicted that LINC-PINT might be a tumor suppressor in GBM." (PMID 33505307, 2020). "Moreover, the tumor weights from LINC-PINT-overexpressed group were also significantly reduced." (PMID 31921860, 2019). "Meanwhile, given the crucial impact of TMB and MSI alterations on the efficacy and outcomes of immunotherapies, our research findings have revealed compelling connections between LINC-PINT alterations and TMB as well as MSI in select tumor types." (PMID 38553526, 2024). "Thirdly, LINC-PINT exerts regulatory control over specific pathways, such as the ATM/ATR-Chk1/Chk2 pathway, significantly influencing tumor cell DNA repair mechanisms." (PMID 38553526, 2024). "In 66 patients with CRC, lncRNA AGAP2-AS1 was significantly overexpressed in the tumor tissues compared to para-tumor normal tissues, whereas LINC-PINT expression was significantly downregulated and negatively correlated with AGAP2-AS1 expression." (PMID 38226210, 2024). "Although the tumor-suppressive function and downregulation of LINC-PINT in different cancers have been thoroughly established, its clinical use remains extremely limited." (PMID 37006616, 2023). "In order to explore the role of LINC-PINT, AC108449.2 and AC007637.1 in the starvation-induced tumor microenvironment, we firstly established an HBSS-induced starvation model in vitro and detected the expression levels of LINC-PINT, AC108449.2 and AC007637.1." (PMID 37341994, 2023). "Additionally, our data revealed LINC‐PINT could depress tumor growth in vivo." (PMID 31981466, 2020). "The results showed that overexpression of LINC-PINT suppressed tumor invasion and migration and downregulation of LINC-PINT increased tumor invasion and migration in U87 and LN229 GBM cell lines." (PMID 33505307, 2020). "Moreover, the re-expression of linc-PINT and HMOX1 is observed upon treatment of ALL with epigenetic drugs, and therefore, it may be one of the molecular mechanisms induced by these drugs to cause anti-tumor effects in this disease." (PMID 29560114, 2018). "While the exploration of potential pathways in which LINC-PINT may be involved has been conducted the precise regulatory mechanisms through which LINC-PINT participates in tumor modulation remain elusive." (PMID 38553526, 2024).
tumor (continued). "Thirdly, this study predominantly focused on examining LINC-PINT expression in tumor tissues, leaving the potential of LINC-PINT as a non-invasive diagnostic or prognostic biomarker in circulation unclear." (PMID 38553526, 2024). "Taken together, these findings suggest that LINC-PINT was downregulated in NPC and may act as a tumor suppressor." (PMID 33963177, 2021). "As shown in tumor xenograft experiment, LINC-PINT suppressed GBM proliferation in vivo." (PMID 33505307, 2020). "In conclusion, our study first demonstrated that LINC-PINT was downregulated in GBM cell lines and could suppress tumor proliferation, invasion, and epithelial-to-mesenchymal transition by blocking Wnt/β-catenin signaling in GBM." (PMID 33505307, 2020). "We firstly demonstrated that LINC-PINT was downregulated in GBM cell lines and could suppress tumor proliferation, invasion, and epithelial-to-mesenchymal transition by blocking Wnt/β-catenin signaling in GBM." (PMID 33505307, 2020). "To investigate whether the tumor behavior could be significantly altered by this novel transcript of LINC-PINT, we first overexpressed LINC-PINT by using control cell lines, which was transfected with virus carrying an empty pcDNA3.1 vector." (PMID 31921860, 2019). "Notably, the levels of LINC-PINT released by tumor cells into the blood could also be used to measure therapeutic responses, as specific anti-cancer drugs induce the re-expression of LINC-PINT." (PMID 37006616, 2023). "Additionally, one lncRNA LINC-PINT remained down-regulated in GBM of patients who received radiotherapy, but its expression was reversed in GBM of patients who received TMZ/radiotherapy compared with non-tumor brain tissues." (PMID 35313638, 2022). "The previous experiment showed that LINC-PINT suppressed tumor invasion and migration of GBM cell lines in vitro, and then we performed further tumor xenograft experiment and tumor peritoneal metastasis experiment to testify the biological function of LINC-PINT in GBM in vivo." (PMID 33505307, 2020). "RNAi‐mediated depletion of LINC‐PINT exacerbated the death of cultured N2A and SH‐SY5Y cells exposed to oxidative stress, highlighting a previously undiscovered neuroprotective role for this tumor‐inducible lncRNA in the brains of patients with neurodegenerative disorders." (PMID 32080970, 2020). "When LINC-PINT overexpressing HCT116 and A549 cells were injected subcutaneously into two different types of immunocompromised mice (nude and BALB/c-Rag2/‐IL2cc), they presented a decreased ability to form tumors, indicating that LINC-PINT inhibits the aggressiveness of the tumor cells." (PMID 29078818, 2017).